LDHA (lactate dehydrogenase A)
Diseases named in the same sentence as LDHA in open-access papers (continued):
Sharing a sentence is not in itself a finding about the gene and the disease.
cancer (continued). "Lactate dehydrogenase A (LDHA) is the main enzyme regulating the Warburg effect, and is thus, a major target for novel anti-cancer drug development." (PMID 30850682, 2019). "Lactate dehydrogenase A (LDH-A) is a key enzyme during glycolysis, which increases the synthesis of related proteins and has elevated activity in cancer cells." (PMID 30509961, 2019). "Another important factor that is positively regulated with cancer invasiveness and EMT is lactate dehydrogensase a (LDHa), a rate limiting enzyme converting pyruvate to lactate during aerobic glycolysis." (PMID 31849832, 2019). "The SplitLuc CETSA assay was further miniaturized to a 1,536-well format for quantitative high-throughput screening (qHTS) using lactate dehydrogenase A (LDHA), a metabolic target for various cancers." (PMID 29930256, 2018). "Numerous glycolytic enzymes such as HK-2, PFK2, PKM2, LDHA, and PDK, have been reported to be rate-limiting factors that are dysregulated in various types of cancer." (PMID 30602670, 2018). "Cancers can also be more dependent on isoforms of hexokinase (HK2) and lactate dehydrogenase (LDHA), or overexpress an isoform of phosphoglycerate mutase (PGAM1)." (PMID 30456204, 2018). "Cancer cells up-regulate the rate-limiting enzymes of glycolysis such as GLUT1, HK2, PKM2, and LDHA as a result of the expression of oncogenes including RAS, SRC, or EGFR." (PMID 29559564, 2018). "Lactate dehydrogenase A (LDHA) is a glycolytic enzyme that is essential for cancer energy metabolism, and it is highly expressed in cancer cells and correlated with poor survival." (PMID 28915924, 2017). "Lactate dehydrogenase A (LDH-A) is an enzyme which uses lactate for energy production and NAD+ regeneration, which is a novel therapeutic target for cancer." (PMID 28946660, 2017). "A previous study showed that miR-34a, miR-34c, miR-369-3p, miR-374a, and miR-4524a/b can targetedly regulate Lactate dehydrogenase A and influence the glycolysis in CRC, suggesting an important role of miRNAs in cancer glucose metabolism." (PMID 28947960, 2017). "MYC is involved in regulating many metabolic enzymes, such as LDHA and HK2 for glycolysis, in cancer cells." (PMID 28474697, 2017). "SIRT2 activates lactate dehydrogenase A (LDH-A) and the increased amount of LDH-A was noted in many cancer cells." (PMID 28197299, 2017). "LDHA is known to be regulated by other oncogenes such as HIF-1a during cancer progression, thus cancer cells have expanded regulatory mechanism to confer metabolic advantages in the advanced stages of diseases." (PMID 27150057, 2016). "Although previous studies showed that c-Myc is critical to regulate LDHA expression and promote cancer progression, however, in our models, CREB is more important for LDHA upregulation in 14-3-3ζ-overexpressing hMECs." (PMID 27150057, 2016). "Seminal studies on the c-Myc oncogene demonstrated that c-Myc can increase the expression of genes involved in glycolysis, such as lactate dehydrogenase-A (LDH-A) and glucose transporter 1 (GLUT1), and stimulate glycolytic metabolism of cancer cells." (PMID 25988385, 2015). "The enzyme lactate dehydrogenase-A (LDH-A), which catalyses the interconversion of pyruvate and lactate, is up-regulated in human cancers, including GBM." (PMID 26494310, 2015). "Marked increase of LDHA, MCT1/4 and CD147 levels correlate with cancer progression and drug resistance and the targeting of LDHA and MCT has been proposed as a cancer therapy." (PMID 25909219, 2015). "NDRG2 inhibited glucose transporter 1, and three key regulatory enzymes HK2, PKM2 and LDHA in glycolysis, NDRG2 also inhibited glutamine transporter ASCT2 and glutaminase GLS1 in glutaminolysis, along with the inhibition of c-Myc in cancer cells." (PMID 26317652, 2015).
cancer (continued). "Both major consumers (LDHA, FASN) and producers (GAPDH, MTHFD and MDH2) of NAD(P)H are subject of major research efforts as drug targets against cancer." (PMID 25621879, 2015). "Lactate dehydrogenase A (LDHA) is an important enzyme in fermentative glycolysis, generating most energy for cancer cells that rely on anaerobic respiration even under normal oxygen concentrations." (PMID 24466056, 2014). "For investigation of proliferating cancer cells and its relation to metabolic characteristics, we performed correlation analysis of Ki-67 with GLUT-1, HK 2, LDHA, TKTL1, SDHA, SDHB, and ATP synthase in OSCC." (PMID 25048361, 2014). "In comparison to normal tissue and hyperplasia a significantly (p < 0.05) increased expression of IGF-R1β, GLUT-1, HK 2, TKTL1, LDHA, SDHA, SDHB, and ATP synthase was observed in cancer cells of OSCC." (PMID 25048361, 2014). "Specific inhibition of LDHA, and the dominant LDH isoform in cancer, is a clear goal in cancer research." (PMID 24363178, 2014). "Among the numerous enzymes participating in the glycolysis, lactate dehydrogenase A (LDH-A), an isoform of lactate dehydrogenase, is undoubtedly an remarkable anti-cancer target with great developable potential." (PMID 25361010, 2014). "Many studies have demonstrated an increase in the activities of the glycolytic enzymes such as hexokinase, lactate dehydrogenase A (LDH-A), and glyceraldehydes-3-phosphate dehydrogenase (GAPDH) in various types of tumors and cancer cell lines." (PMID 22844340, 2012). "Additionally, it has been documented that the phosphorylation of LDHA is regulated by FGFR1, a membrane receptor tyrosine kinase frequently overexpressed in various cancers." (PMID 41531896, 2026). "Genes like PGK1, PFKP, HK2, and LDHA, that are involved in metabolic reprogramming of cancer cells by enhancing glycolysis have a negative correlation with PEBP1/STK11 co-expression." (PMID 40806276, 2025). "By inhibiting lactate metabolism, particularly through LDHA inhibitors, the lactylation of NBS1 at K388 can be effectively reduced, overcoming chemotherapy resistance, and markedly improving the prognosis of patients with cancer." (PMID 40177399, 2025). "Lactate dehydrogenase A (LDHA) is an aerobic glycolysis rate restrictor, catalyzing the reversible interconversion between pyruvate and lactate and NADH and NAD+, providing energy for cancer cells." (PMID 40865948, 2025). "This underscores the therapeutic necessity of targeting both LDHA and LDHB in cancer." (PMID 40940446, 2025). "In contrast, cancer cells catalyze the conversion of pyruvate to lactate via the enzyme Lactate Dehydrogenase A (LDHA), regardless of oxygen availability." (PMID 40746883, 2025). "Enzymes like LDHA and HK2, crucial for lactate production, are overexpressed in many cancers." (PMID 40433363, 2025). "We identified a robust upregulation of GLUT1 (SLC2A1), a key rate-limiting factor in the transport of glucose in cancer cells, and genes involved in central glucose metabolism (HK2, ENO1, PKM, and LDHA), PPP (G6PD), and de novo serine biosynthesis pathway (PSAT1, PSPH, and SHMT2)." (PMID 40371988, 2025). "LDHA is essential in converting pyruvate to lactate, which not only supports cancer growth but also serves as a signaling molecule that promotes angiogenesis, invasion, migration, and immune evasion." (PMID 41235096, 2025). "Specifically, the expression of LDHA was approximately doubled in the UBD high‐expression group, suggesting that UBD may enhance the metabolic activity of cancer cells by promoting lactate production at the end of the glycolytic pathway." (PMID 40692714, 2025). "Although the relationship between LDHA and gemcitabine resistance in CCA has not been directly reported, evidence from other cancers suggests that LDHA plays a critical role in gemcitabine resistance." (PMID 41425711, 2025). "Two isoforms, LDHA and LDHB, exist, each exhibiting a dual role in cancer metabolism." (PMID 38198170, 2024).
cancer (continued). "A combination therapy involving the LDHA inhibitor FX11, and piezoelectric WS2 nanosheets, which can be activated by ultrasound for PzDT, could offer a more effective treatment strategy for cancer." (PMID 39479443, 2024). "designed a novel dual-functional ligand that inhibits LDHA, with activity 9 times higher than sodium oxalate,however, subsequent reports on detailed molecular modeling studies and biological tests targeting cancer cell lines have not been forthcoming." (PMID 39877360, 2024). "An LDHA inhibitor (GSK2837808A), IR780, and calcium is integrated which is a multifunctional therapeutic agent that operates on several fronts to enhance the immune response against cancer." (PMID 39479443, 2024). "Key enzymes in glycolysis such as glucose transporter 1 (GLUT1), hexokinase 2 (HK2), phosphoglycerate kinase 1 (PGK1), pyruvate kinase M2 (PKM2), lactate dehydrogenase A (LDHA), and monocarboxylate transporter 4 (MCT4) have been observed to be highly expressed in cancer tissues." (PMID 39594816, 2024). "This complexity underscores the need for a deeper exploration of the non-canonical functions of these enzymes, as exemplified by the metabolic enzyme LDHA, which has been shown to activate Rac1 GTPase through non-traditional mechanisms to promote cancer." (PMID 38989284, 2024). "Among the numerous enzymes involved in glycolysis, LDHA, a key enzyme in aerobic glycolysis, catalyzes the mutual conversion of lactate and pyruvate, along with the interconversion of NADH and NAD+, making it a promising anti-cancer target." (PMID 39680520, 2024). "Moreover, our study shows that NAT10 functions as a cancer-promoting molecule by targeting the glycolysis genes PFKM and LDHA directly or indirectly through acetylation in mRNA to reduce glycolysis breakdown and inhibit tumorigenesis." (PMID 38233839, 2024). "A recent study showed that ASP extract effectively reduced the activities of G6PD, LDHA, PKM2, c-Myc, and glutaminase in HepG2 cells, suggesting that ASP may inhibit glycolysis and glutamine metabolism in cancer cells." (PMID 39697544, 2024). "In addition, mounting evidence suggests that HIF‐1α can increase glycolysis in cancer by upregulating the expression of downstream targets such as PDK1 and LDHA, which are glycolytic‐related genes." (PMID 38229475, 2024). "In this metabolic process, pyruvate is converted to lactate by LDHA, which is also deregulated in CCA in a GLUT5-expression-dependent manner, indicating that elevated GLUT5 levels result in increased lactate production in cancer cells." (PMID 39107723, 2024). "CXCL1 increases cancer cell proliferation and increases glycolytic enzyme expressions, such as glucose transporter 1 (GLUT1), hexokinase 2 (HK2), and lactate dehydrogenase A (LDHA)." (PMID 37408240, 2023). "CENPE and LDHA were identified as the important prognostic biomarkers in KICH, and they might be involved in the proliferation of cancer cell." (PMID 37925501, 2023). "In the lactate fermentation pathway, ARV σA protein suppresses lactate dehydrogenase A (LDHA), implying the Warburg effect does not occur in these cancer cell lines." (PMID 36851737, 2023). "Lactate dehydrogenase, LDHA, and LDHB are important targets for cancer therapy." (PMID 37762231, 2023). "Except for LDHA and LDHB, LDHC and LDHD are expressed in various cancers." (PMID 37547725, 2023). "LDHA is a member of the lactate dehydrogenase (LDH) family, which includes central players in glycolysis and is known to be involved in the development and progression of cancer through lactate production." (PMID 37733442, 2023). "Cancer cells treated with a high glucose concentration induce the expression of MORC2, which interacts with c-Myc and gets recruited onto the LDHA promoter to increase the transcription of LDHA." (PMID 37892209, 2023). "If there is not sufficient oxygen, lactate dehydrogenase A (LDH-A), the enzyme that is commonly overexpressed in malignant tumors converts pyruvate into lactate." (PMID 37376060, 2023).
cancer (continued). "The normal-like samples did not stain for GLUT1, HK2, and LDHA, with the differences being significant and near-significant with regard to the LDHA and HK2 expression in the cancer sections (44.9% positivity for LDHA, p = 0.018; 35.5% positivity for HK2, p = 0.050)." (PMID 36765947, 2023). "The positive correlations of DOT1L with BCAT1 (Pearson correlation γ was 0.5202; p < 0.01) and LDHA with BCAT1 (Pearson correlation γ was 0.5202; p < 0.01) were analyzed from gene expression profiles of 549 GBM cases of the Cancer Genome Atlas (TCGA) database, respectively." (PMID 37298317, 2023). "Studies have found that sirtuins can directly interact with genes and enzymes related to glucose metabolism, such as HK2 and lactate dehydrogenase A (LDHA), and/or indirectly regulate the upstream factors or pathways of glycolysis, such as HIF-1/2, to control the level of glycolysis in cancer cells." (PMID 35915188, 2022). "Inhibition of LDHA and HK2 expression suppresses the Warburg effect in cancer cells." (PMID 35256924, 2022). "In contrast to LDHA, LDHB catalyzes the oxidation of lactate to pyruvate, which forms fuel energy for cells in the Krebs cycle, thus contributing to metabolic reprogramming and malignant biological behaviors of cancer cells." (PMID 35757505, 2022). "Whether the different contributions of LDHA and LDHB to histone lactylation is a general feature in cancers requires further efforts." (PMID 35637958, 2022). "HIFs, LDHA and PDH kinases are up-regulated in cancer even under hypoxic conditions." (PMID 36568220, 2022). "Hexokinase 2 (HK2), pyruvate kinase 2 (PKM2), and lactate dehydrogenase A (LDHA) can regulate EMR, and abnormal expression of these enzymes may promote the Warburg effect in cancer cells 5-7." (PMID 35711836, 2022). "Ectopic c-MYC expression could drive aerobic glycolysis in cancers via the direct upregulation of GLUT1, LDHA, HK2, and PKM2." (PMID 35571245, 2022). "Unlike another study, LDHA inhibitor oxamate inhibited protumorigenic cascades in other cancer types." (PMID 36474242, 2022). "In this process, LDHA is a key player responsible for the production of ATP and the regeneration of oxidized NAD, factors necessary for the processes of synthesis that enable cancer cell proliferation and invasion." (PMID 36555705, 2022). "In this regard, some regulatory enzymes, including GLUTs, Hexokinase II (HKII), 6-Phosphofructo-2-kinase (PFKFB3), pyruvate dehydrogenase (PDH), lactate dehydrogenase A (LDHA) and pyruvate kinase M2 (PKM2), should be upregulated to accelerate the rate of glycolysis in cancer cells." (PMID 36230935, 2022). "Transcriptionally, LDHA is regulated by forkhead box protein M1 (FOXM1), hypoxia-inducible factors (HIF-1α and HIF-2α), Jumonji C Domain 2A (JMJD2A), and peroxisome proliferator-activated receptor gamma (PPAR-γ) coactivator 1-beta (PGC1β) in cancer cells." (PMID 35832094, 2022). "The transcription of LDHA is mainly regulated by two transcription factors, i.e., HIF1 and c-MYC (Avian myelocytomatis virus oncogene cellular homolog), which collaborate to activate LDHA transcription in numerous cancer cells." (PMID 36551514, 2022). "HPA analysis showed that the protein levels of LDHA and TES were highly upregulated in cancer tissues compared to normal pancreatic tissue, while those of NDST1, ANKZF1, and SIAH2 were significantly decreased in cancer tissues." (PMID 35935823, 2022). "The enzymes of glycolysis glyceraldehyde-3-phosphate dehydrogenase (GAPDH), enolase 1 (ENO1) and lactate dehydrogenase (LDHA) and glycerol-3-phosphate dehydrogenase (GPD1) which shuttles electrons to mitochondria, revealed a significant increase in carcinomas when compared to NAT." (PMID 35534478, 2022). "To investigate the contributions of HIF-1α in regulating glycolysis of cancer cells under hypoxia, we evaluated the dynamics of HIF-1α protein and its target genes related to glucose metabolism, including GLUT1, HKII, LDHA, and PDK15, following prolonged hypoxia." (PMID 33637716, 2021).